IL13RA2 (interleukin 13 receptor subunit alpha 2)
Diseases named in the same sentence as IL13RA2 in open-access papers (continued):
Sharing a sentence is not in itself a finding about the gene and the disease.
tumor (continued). "Thus, we hypothesise that pre‐treatment of hosts either with HDAC‐inhibitors or CGRPs will synergise with CAR‐T cells in targeting IL‐13Rα2 positive solid cancer for a better anti‐ tumour effect." (PMID 38685487, 2024). "Additionally, recent studies have identified that protein tyrosine phosphatase-1B inhibitors inhibit IL13 signal transduction, attenuating the invasive and migratory capabilities of IL13Rα2-positive GBM tumor cells, showing promising therapeutic potential in animal experiments." (PMID 38201655, 2024). "Therefore, in this context, it is suggested that IL-13 induction might be a common mechanism of tumor resistance, with IL-13Rα2 contributing to resistance as the receptor for IL-13." (PMID 39598436, 2024). "Furthermore, HDAC or DNMT inhibition selectively upregulated IL-13Rα2 expression and enhanced the effectiveness of Pep-1-Phor21 against tumor cells, raising the possibility that a combination drug therapy approach may be particularly effective." (PMID 37345109, 2023). "Trivalent CAR-T cells co-targeting HER2, IL-13Rα2, and EphA2 could overcome interpatient variability, achieve a capture of antigens in nearly 100% of tumor cells, avoid antigen escape, and were shown to increase the survival in an orthotopic xenograft model of GBM." (PMID 37443804, 2023). "In addition to directly killing tumour cells, IL-13Rα2-targeting CAR-T cells may eliminate other IL-13-responsive cells in the tumour microenvironment contributing to therapeutic efficacy." (PMID 37455828, 2023). "Recent investigations have elucidated the role of IL-13Rα2 as a tumor-associated antigen that mediates aberrant STAT3 signaling, driving increased expression of anti-apoptotic genes and, ultimately, promoting tumor progression by blocking cell death and mediating survival." (PMID 35631512, 2022). "Immunization with IL13RA2 DNA vaccine could inhibit tumor growth and induces tumor immunity." (PMID 33859933, 2021). "Mouse cells express a soluble form of IL13Rα2, which might interfere with the antibody to deplete extracellular IL-13, as secreted IL13Rα2 may bind the antibody in the circulation and could prevent sufficient antibody from binding to the tumor." (PMID 33917458, 2021). "Thus, YYB-103 CAR T cells may show improved preferential cytotoxic effects toward IL13Rα2-expressing tumor cells." (PMID 34819930, 2021). "IL-13Rα2 is localized mainly on the tumor cell surface and its expression is positively corelated with the severity of the disease, including an advanced tumor stage and the pathological grade, suggesting that IL-13Rα2 may have a critical role in tumor progression." (PMID 34201539, 2021). "Interestingly, treatment with IL-13Rα2-directed CAR T cells may evoke host immune responses to the tumor." (PMID 35011583, 2021). "Interestingly, a recent study demonstrated that EGFRvIII, due to its tumor-specific expression, can be successfully used in a SynNotch-CAR system, where it is responsible for turning on the expression of a dual-antigen–targeting CAR (IL13Rα2 and EphA2) at a tumor site." (PMID 34760690, 2021). "Additionally, it is also seen that there is the effective killing of GB cancer cells with the NSCs modified with BiTEs, specifically the promotion of T-cell killing of IL13Rα2+ tumor cells by engaging the tumor cell antigen with CD3 epsilon T cells that effectively target them." (PMID 35011678, 2021). "As an example, for the case of GBM the tumour-associated antigen could be IL13Rα2, which is associated with poor prognosis and is over-expressed in >60% of those tumours, but not on normal brain tissue." (PMID 33572301, 2021). "In addition, these studies revealed that overexpression of IL13RA2 could confer invasive and metastatic ability on tumor cells." (PMID 31823484, 2020).
tumor (continued). "Interestingly, a greater number of tumor samples with invasion to Ne rather than PL were significantly associated with enhanced IL-13Rα2 detected by IHC and mRNA (ISH) (P ≤ 0.0001) in PDAC patients with a moderate to poor pathologic grade." (PMID 32443847, 2020). "Silencing of IL13RA2 promoted tumor cell migration via intrinsic phosphorylation of extracellular signal‐regulated kinase, and The Cancer Genome Atlas analysis suggests that IL13RA2 may be a potential prognostic biomarker of long‐term survival for patients with HCC." (PMID 31823484, 2020). "In order to determine whether expression of amphiregulin transcript is also upregulated by IL13Rα2, we performed qRT-PCR analyses for the expression of IL13Rα2 and amphiregulin using the cDNAs prepared from tumours originated from SK-MEL-28 and SK-IL13Rα2 cells." (PMID 30718742, 2019). "However, the upstream signaling mechanisms that promote aberrant IL13Rα2 expression during tumor progression remain unknown." (PMID 30805303, 2019). "Moreover, they can identify and reject tumor antigens such as HER-2 or IL13Rα2." (PMID 30248992, 2018). "Hence, LBA was used to determine the amount of IL13Rα2 Ab in the tumor, for all the groups." (PMID 28915667, 2017). "In addition, targeting YKL-40 receptor IL-13Rα2 is also anticipated to serve as a potent alternative strategy for either blocking YKL-40-induced tumor vascularization or eliciting a synergetic effect in conjunction with mAY." (PMID 26439689, 2015). "Indeed, experiments in an orthotopic mouse model of pancreatic cancer suggest that IL-13Rα2 is an important mediator of the pro-tumor effects of IL-13, including activation of AP-1 growth signals, production of immunomodulatory cytokines such as TGF-β, and promotion of metastasis." (PMID 24672527, 2014). "We observed that IL-13-PE could significantly decrease tumor size in both IL-13Rα2-positive tumors." (PMID 21477288, 2011). "However, the IL-13Rα2 DNA and ECDα2 boost vaccination could be effective in reducing tumor burdens and induce or amplify a specific CTL response and IFN-γ release against 4T1 tumors compared with the IL-13Rα2 DNA vaccine alone." (PMID 21067607, 2010). "In this study, we investigate in vitro combination of IL-13Rα2 targeted CAR T-cells with an oncolytic virus (OV) and study the complex interplay between tumor cells, CAR T-cells, and OV dynamics with a novel mathematical model." (PMID 39896563, 2025). "IL13Rα2 expressed in over 50% of GBM patients, which has emerged as one of the most promising CAR-T targets for GBM, promotes tumor progression by inhibiting the STAT6 signaling pathway." (PMID 40386781, 2025). "The relative overexpression of IL13RA2 and underexpression of CXCL11 and IFNA7 also imply tumor-related chronic inflammatory suppressive TME which would support immune evasion." (PMID 41511314, 2025). "Together, IL-13Rα2 and CD16 establish complementary recognition-activation circuitry within the TME: IL-13Rα2 confers tumor-specific binding, whereas CD16 triggers NK-cell cytotoxicity." (PMID 41209565, 2025). "A recent study engineered a TanCAR targeting both IL-13Rα2 and TGF-β, designed to reprogram tumor-specific T cells to convert TGF-β from an immunosuppressant to an immunostimulant." (PMID 40092990, 2025). "For instance, tumor cells expressing either antigen can be bound and killed separately by CAR T-cells that are designed to target both IL-13Rα2 and B7-H3, an immunological checkpoint protein produced by GBM cells." (PMID 40585996, 2025). "In conclusion, the exploration of IL-13Rα2 and EphA2 within the context of BCA has highlighted their pivotal roles in tumor progression, metastasis, and the development of resistance mechanisms." (PMID 38612592, 2024). "In vitro, TanCAR-T cells showed cytolytic activity against all tested tumor cells (HER2+, IL-13Rα2+, HER2+ and IL-13Rα2+)." (PMID 38339374, 2024).
tumor (continued). "The results revealed that local intracranial administration of IL-13Rα2-targeted CAR-T-cell therapy in combination with recombinant human IL-2 was well tolerated and resulted in transient tumor reduction or necrosis at the infusion site in four patients." (PMID 39406966, 2024). "CHI3L1 interacts with CD44 and IL-13Ra2, activating pathways such as AKT and ERK1/2, which in turn promote tumor growth and invasion." (PMID 38177294, 2024). "The in vitro results confirmed that TanCAR-T cells showed superior efficacy against tumor cells containing only the sole target antigen compared to monospecific CAR-T cells (i.e., anti-EGFRvIII CAR-T cells and anti-IL-13Rα2 CAR-T cells)." (PMID 38339374, 2024). "ICT-107 is an autologous DC vaccine targeting six tumor antigens (MAGE-1, HER-2, AIM-2, TRP-2, gp100, IL-13Rα2) specifically overexpressed in glioma stem cells." (PMID 38473776, 2024). "Subsequent expression of the IL-13Rα2/EphA2 CAR upon binding to the priming antigens induced spatially controlled and tumour-specific T-cell cytotoxicity in patient-derived in vivo models of GBM." (PMID 38615034, 2024). "In the present study, we observed a significant level of IL‐13Rα2 gene silencing retained in U251 KD and U87MG KD tumour cell lines for up to 35 days (P ≤ .0001)." (PMID 38685487, 2024). "As a secondary objective of this trial, IL-13Rα2-CAR-T cell persistence in cerebrospinal fluid (CSF), tumor cavity fluid (TCF) and blood was monitored throughout treatment." (PMID 38454126, 2024). "Studies targeting antigens such as IL13Rα2, EGFRvIII, and HER2 have shown remarkable tumor regression and improved survival rates in patients." (PMID 38255798, 2024). "For instance, in a preclinical glioma model, IL-15 expression led to increased persistence and proliferative capacity of IL-13Rα2-CAR-T cells, resulting in enhanced anti-tumor activity." (PMID 38932383, 2024). "Levels of IL‐13Rα2 mRNA were still less than 10% in U251KD and U87MG KD xenografts compared to U251 and U87MG tumours (P ≤ .0001) at the end of the experiment." (PMID 38685487, 2024). "Our results are clinically actionable, as IL13Rα2-targeting CAR T cells are currently being studied in clinical trials in recurrent GBM, where radiation is typically used to control tumor progression." (PMID 38994929, 2024). "The potency of CAR‐T cells was first assessed by cell killing assay against IL‐13Rα2 positive U251 and U87MG malignant glioma tumour cells lines, as these tumour cell lines express high levels of IL‐13Rα2." (PMID 38685487, 2024). "The results revealed higher relative expression levels of IL13Ra2, Ki67, and CD133 in the H3K27M tumor tissues." (PMID 38201655, 2024). "This makes IL13Ra2 an especially attractive antigen to target GBM cells and mitigate the on-target off-tumor toxicity of targeted immunotherapeutics." (PMID 37443750, 2023). "However, loss or decrease of antigen in tumor cells has become the main obstacles for EGFRvIII’s further study, and overlapping of the antigen expression on normal tissues has caused off-target side-effects in patients receiving CAR-T cells targeting IL13Rα2 and EphA2." (PMID 37481592, 2023). "Overexpression of IL13 Rα2 activates the phosphatidylinositol-3 kinase/AKT/mammalian target of rapamycin pathway, leading to poor prognosis and increased tumor invasiveness in GBM." (PMID 36874119, 2023). "Another patient treated with intraventricular IL13Rα2 CAR T therapy had initial resolution of multifocal GBM, until eventual relapse of disease with tumor cells showing decreased expression of the IL13Rα2 protein." (PMID 36900205, 2023). "It has been found that in vitro and xenograft mouse models transfected with human-derived anti-IL-13Rα2 CAR and murine anti-IL-13Rα2 CAR human-derived CAR-T cells have better amplification ability and more effectively inhibit the growth of GBM tumor cells." (PMID 37190280, 2023).
tumor (continued). "The mRNA expressions of the majority of genes, including IL13RA2, IL20 and SAA2, were persistently higher in tumor cells lines than Het-1A cells." (PMID 37430202, 2023). "Lin also demonstrated that IL-13Rα2 was over-expressed in GBM and that a nano-delivery system constructed utilizing Pep-1 was efficient at impeding tumor proliferation via the regulation of the JNK signaling pathway." (PMID 36744246, 2023). "While still an active area of clinical study in GBM, target tumor antigens have included EGFR/EGFRvIII, IL13Ra2, and HER2." (PMID 36828374, 2023). "To understand how differences in antigen density impact tumor killing, we established a GBM line with low and high IL13Rα2 levels." (PMID 36968221, 2023). "The earliest preclinical studies were conducted with CAR T cells targeting EGFRvIII, IL13Ra2, and HER2 and had impressive rates of tumor control and improved survival in murine models, leading to the design of multiple clinical trials." (PMID 37754534, 2023). "The combined down-regulation of RELA and MMP9 expression upon SHN3 silencing inhibits tumor growth and cancer invasion, supporting a potential therapeutic value for SHN3 targeting in IL13Rα2-positive tumors." (PMID 37963919, 2023). "In another trial targeting IL-13Rα2 with specific CAR-T cells, the patient developed a recurrent tumor with decreased antigen expression." (PMID 37443804, 2023). "Christine E. Brown reported an increase in the number of cytokines and immune cells in the CSF and the regression of tumor cells in the spinal canal and spine after studying a patient with recurrent multifocal GBM treated with IL-13Rα2- CAR-T." (PMID 37190280, 2023). "For the same targeted tumor antigen, another clinical trial (NCT00730613) used anti-IL-13Rα2-CAR-T cells for the treatment of 3 patients with recurrent GBM." (PMID 36717905, 2023). "This fact was exploited for the development of the first IL13Rα2-specific CAR, which included a so-called zetakine composed of an extracellular altered IL13 domain and demonstrated effective tumor cell lysis in human xenograft models." (PMID 36303101, 2022). "In order to validate the anti-tumor effects of GB-13 in vivo, we utilized orthotopic patient-derived murine xenograft models of HGG, including IL-13Rα2-low (SU-DIPG XIII-P), IL-13Rα2-medium (GBM6), and IL-13Rα2-high (PED17) models." (PMID 35631512, 2022). "In an early clinical trial (NCT02208362), IL13Rα2-directed CAR-T cells were delivered into the cerebrospinal fluid, and one remarkable patient experienced tumor regression, even though subsequent recurrence emerged." (PMID 35920986, 2022). "One of the responding patients showed reduced IL-13Rα2 expression within tumor tissue after CAR-T cell therapy, and the other patient appeared to have an increase in tumor necrotic volume at the site of CAR-T cell therapy." (PMID 33741903, 2021). "The authors used the CNS- or tumor-specific antigens myelin oligodendrocyte glycoprotein (MOG) or EGFRvIII, respectively, as activating signal for the expression of anti-EphA2 or anti-IL13Ra2 CARs." (PMID 34884607, 2021). "In 272 overall RCCs, age (CSS, P = 0.018), tumor stage (CSS, P = 0.005; RFS, P < 0.001), tumor necrosis (CSS, P = 0.005; RFS, P = 0.015), and IL13Rα2 expression (CSS, P = 0.025; RFS, P = 0.004) were significantly associated with CSS or RFS." (PMID 33917914, 2021). "Transgenic IL-15 expressing IL13Rα2-CAR T cells had greater expansion and enhanced anti-tumor effector function as measured by cytokine production." (PMID 34421912, 2021). "In 201 CCRCCs, age (CSS, P = 0.042), tumor stage (CSS, P = 0.010; RFS, P < 0.001), tumor necrosis (CSS, P = 0.006; RFS, P = 0.054), and IL13Rα2 expression (CSS, P = 0.019; RFS, P = 0.005) were significantly associated with CSS or RFS." (PMID 33917914, 2021).
tumor (continued). "Expression patterns in PBTs are mostly heterogenous with some TAAs more robustly expressed across tumor subtypes (GD2, B7-H3, IL13Rα2), while other targets have variable expression frequencies and intensities (HER2, EphA2, EGFRvIII)." (PMID 34760690, 2021). "This trivalent CAR T cell demonstrated improved anti-tumor activity and survival in GBM patient derived xenografts compared to biCAR (IL13Rα2, andEphA2) and single IL13Rα2 CAR T cells, while lower T cell doses were required to control tumor growth." (PMID 34421912, 2021). "Remarkably, one subject was reported to have a transient complete response to IL-13Rα2-directed CAR T cell treatment, though disease recurrence 228 days after initial CAR T treatment with diminished IL-13Rα2 expression in the tumor was reported." (PMID 35011583, 2021). "ICT-107 is another vaccine tested for GBM that consists in an autologous dendritic cell pulsed ex vivo with tumor and CSC antigens (AIM-2, HLA-A2, HER2, TRP-2, gp100, and IL13Rα2)." (PMID 34557553, 2021). "To determine IL13RA2 expression in human HCC and cell lines, we performed TCGA database analysis, which included 50 normal hepatic tissue samples and 369 tumor samples." (PMID 31823484, 2020). "IL4R is composed of several distinct chains, on several tumor cells IL4Rα and IL13Rα’ chains are expressed and bind IL4, while in many solid tumor IL13 binds the chains IL-4Rα and IL13Rα1 and IL13Rα2." (PMID 32957689, 2020). "Our data also demonstrate that Activin A signaling induces Smad-depended IL13Rα2 expression and that knocking down INHBA levels delays primary tumor growth and suppresses formation of lung metastases in vivo." (PMID 30805303, 2019). "In contrast to the in vitro data, tumours derived from the SK-IL13Rα2 cells were larger than those formed by parental SK-MEL-28 cells, suggesting that high level of IL13Rα2 expression promoted tumorigenicity in vivo." (PMID 30718742, 2019). "Although IL13Rα2 suppressed in vitro proliferation of the SK-MEL-28 cells, the tumours formed by the SK-IL13Rα2 cells grew faster than those derived from the SK-MEL-28 cells." (PMID 30718742, 2019). "Despite these therapeutic alterations, the authors reported that gliomas recurred in their xenograft model displaying lower expression of IL13Rα2, signifying the critical need that CAR-T cells promote immune responses against multiple tumor antigens." (PMID 30740109, 2018). "Hegde, Grada, and colleagues have developed a tandem CAR combining the recognition of IL-13Rα2 and HER2, based on mathematical modeling that predicted 90% tumor killing in GBM patients with this antigen combination." (PMID 30740109, 2018). "The expression of IL-13Rα2 and EGFR proteins was confirmed in primary tumor samples from Singaporean patients with GBM." (PMID 29203859, 2017). "Two commonly expressed tumor antigens in GBM include the epidermal growth factor receptor mutant (EGFRvIII) and the interleukin-13 receptor alpha 2 (IL-13Rα2), which are potential targets for the treatment of GBM2,3." (PMID 29203859, 2017). "We found significant anti-tumor effects of [225Ac]Pep-1L in these initial experiments, which we are continuing to investigate in GBM and other cancer models that express IL13RA2." (PMID 28562337, 2017). "In addition, high IL13Rα2 expression could specifically predict metastasis-free survival of patients with high- but not low-grade tumors, suggesting that overexpression of this gene may be involved in promoting the late stages of tumor progression." (PMID 26208975, 2015). "The TAZ protein level is elevated in tumor cells via increased PI3K signaling, which raises the possibility that IL13Rα2 activates the TAZ pathway through PI3K." (PMID 26418721, 2015). "Having identified the efficacy of the IL-13Rα2 DNA and ECDα2 boost vaccination in the prevention of MCA304, 4T1, and D5α2 tumor growth, we tested efficacy of this vaccine in mice with established tumors to simulate a clinical situation." (PMID 21067607, 2010).